ZFP91 (ZFP91 zinc finger protein, atypical E3 ubiquitin ligase)
Description:
DNA-binding transcription factor. Also acts as an atypical E3 ubiquitin-protein ligase that mediates 'Lys-63'-linked ubiquitination of MAP3K14/NIK, leading to stabilize and activate MAP3K14/NIK. It thereby acts as an activator of the non-canonical NF-kappa-B2/NFKB2 pathway. May also play an important role in cell proliferation and/or anti-apoptosis.
Synonyms: Zfp-91; ZNF757; FKSG11; PZF; DMS-8; DSM-8; DSM8
Tractability: PROTAC: ubiquitination databases record sites on it; its protein half-life has been measured.
Target class: Enzyme; Transferase
Gene: Protein-coding gene on chromosome 11 (58,578,476 to 58,621,550, forward strand). Ensembl gene ENSG00000186660.
Subcellular location: Nucleus
Subcellular location (Human Protein Atlas): Nucleoli; Nucleoplasm
Gene Ontology:
Molecular function: DNA-binding transcription factor activity, RNA polymerase II-specific; protein binding; ubiquitin protein ligase activity; ubiquitin-protein transferase activity
Biological process: activation of NF-kappaB-inducing kinase activity; positive regulation of transcription by RNA polymerase II; protein K63-linked ubiquitination; regulation of transcription by RNA polymerase II; protein ubiquitination
Cellular component: nucleolus; nucleoplasm; nucleus
Genetic constraint (gnomAD): Loss-of-function variants: 6 observed, 50.03 expected, observed/expected ratio (o/e) 0.12, 90% interval 0.065 to 0.24. The synonymous counts are far from expectation, so gnomAD's model fits this gene poorly and the ratio says little. Missense variants: 615 observed, 694.15 expected, observed/expected ratio (o/e) 0.89, 90% interval 0.83 to 0.95. Synonymous variants: 326 observed, 263.45 expected, observed/expected ratio (o/e) 1.24, 90% interval 1.13 to 1.36.
Homologues: Orthologues: chimpanzee ZFP91 (99% identical), macaque ZFP91 (99% identical), pig ZFP91 (96% identical), mouse Zfp91 (92% identical), rat Zfp91 (91% identical), dog ZFP91 (90% identical), rabbit ZFP91 (78% identical), guinea pig ZFP91 (75% identical), tropical clawed frog zfp91 (51% identical), zebrafish zfp91 (44% identical), zebrafish znf692 (24% identical), zebrafish im:7147486 (15% identical). Paralogues in human: ZNF692 (25% identical), ZNF653 (21% identical), ZNF276 (21% identical), PRDM1 (14% identical), PRDM10 (13% identical), MTF1 (12% identical), ZNF384 (12% identical), ZNF451 (12% identical), ZNF148 (12% identical), ZNF76 (12% identical), PATZ1 (11% identical), ZBTB7C (11% identical), and 24 more.
Diseases named in the same sentence as ZFP91 in open-access papers:
ZFP91 is named in the same sentence as 30 diseases in open-access papers, as found by Europe PMC text mining. Sharing a sentence is not in itself a finding about the gene and the disease. The quoted sentences say what the papers report.
colon cancer (12 papers, 2016 to 2023). "In human gastric cancer, down‐regulation of FOXA1 by the E3 ligase ZFP91 has been associated with promotion of chemoresistance, while in colon cancer down‐regulation of FOXA1 via NEDD4 promoted EMT and metastasis." (PMID 37491794, 2023). "The key findings of this study are that ZFP91 overexpression was significantly associated with progression of human colon cancer and that ZFP91 promotes colon cancer progression through upregulating HIF-1α in cooperation with NF-κB/p65." (PMID 27144516, 2016). "Furthermore, ZFP91 is positively associated with HIF-1α in human colon cancer." (PMID 27144516, 2016). "It has been disclosed that ZFP91 boosts prostate cancer propagation via the NF-κB pathway and tumorigenesis of colon cancer by the upregulation of the HIF-1α level 18,29." (PMID 35165513, 2022). "Zinc finger protein 91 (ZFP91), a novel E3 ubiquitin ligase, is demonstrated to be upregulated in prostate cancer, colon cancer and pancreatic cancer." (PMID 33755268, 2021). "It has been reported that ZFP91 plays an oncogene role in various tumors, including gastric cancer, pancreatic cancer, and colon cancer." (PMID 34925523, 2021). "It is reported that ZFP91 facilitates prostate cancer proliferation via NF‐κB pathway and tumorigenesis of colon cancer by upregulating HIF‐1α level." (PMID 33755268, 2021). "Jin and his co‐workers found that zfp91 protein was overexpressed in these patients with colon cancer." (PMID 32677376, 2020). "Upregulation of ZFP91 is reported to enhance tumorigenesis in a colon cancer cell line through promotion of hypoxia-inducible factor-1 gene expression." (PMID 32517689, 2020). "In summary, we report that ZFP91 promotes colon cancer progression through upregulating HIF-1α via NF-κB/p65." (PMID 27144516, 2016). "Most recently, it has been shown that ZFP91 is overexpressed in human colon cancer and promotes this cancer progression." (PMID 27975057, 2016). "In this regard, we found another crucial role of ZFP91 other than NIK activation in cancer: ZFP91 was able to dramatically upregulate the expression levels of HIF-1α in colon cancer cells." (PMID 27144516, 2016). "This study advances our knowledge of the activation mechanism of HIF-1α and indicates that ZFP91 plays an important, yet previously unappreciated, role in the tumorigenesis and progression of colon cancer." (PMID 27144516, 2016). "The human colon cancer specimens exhibited a robust expression of ZFP91 and HIF-1α compared with adjacent tissues." (PMID 27144516, 2016). "In this study, we found that ZFP91 expression was significantly upregulated in colon cancer cells and tissues." (PMID 27144516, 2016). "Furthermore, it was demonstrated that ZFP91 promotes colon cancer cell proliferation by activating HIF-1α via NF-κB/p65 and leading to a significant increase in the proportion of cells in the S phase." (PMID 36358661, 2022). "By means of ChIP, EMSA gel migration and luciferase reporter assays, it was found that ZFP91 could cooperate with NF‐κB/p65 to transcribe hypoxia inducible factor‐1 to regulate development of colon cancer." (PMID 32677376, 2020). "Another pathway through which ZFP91 may promote angiogenesis is hypoxia-induced factor 1α (HIF1α), which is strongly upregulated by ZFP91 in colon cancer cells." (PMID 32630670, 2020). "Whether ZFP91 also regulates the K48 ubiquitination and degradation of hnRNP A1 in AML, prostate and colon cancers and other cancers with ZFP91 expression upregulation remains to be explored in the future." (PMID 32754263, 2020). "ZFP91 is an atypical E3 ubiquitin-protein ligase that is upregulated in or promotes cancers such as acute myelogenous leukemia, prostate cancer, gastric cancer, and colon cancer." (PMID 31841561, 2019). "Therefore, we asked how ZFP91 can promote proliferation and tumorigenesis in colon cancer cells in vitro and in vivo." (PMID 27144516, 2016). "Our data suggests that ZFP91 promotes the proliferation of colon cancer cells through HIF-1α." (PMID 27144516, 2016).
colon cancer (continued). "More importantly, our finding suggests that ZFP91 may serve as a transactivator to play crucial roles in the development of colon cancer." (PMID 27144516, 2016). "More understanding of the precise role of ZFP91 in human cancer may provide the opportunity to develop a novel therapeutic strategy by suppressing expression of ZFP91 in colon cancer cells." (PMID 27144516, 2016). "We found that ZFP91 was significantly upregulated in a large cohort of human colon cancer tissues." (PMID 27144516, 2016). "Moreover, in 27.27% of human colon cancer, ZFP91 and HIF-1α were collectively up-regulated (p=0.009)." (PMID 27144516, 2016). "Our results show that ZFP91 functions as an oncoprotein in the colon cancer progression and may provide a new prognostic marker and therapeutic target for the treatment of colon cancer." (PMID 27144516, 2016). "Here, we show that ZFP91 expression is upregulated in patients with colon cancer." (PMID 27144516, 2016). "Thus, we concluded that ZFP91 is able to activate HIF-1α transcription through interacting with NF-κB/p65 in colon cancer cells." (PMID 27144516, 2016). "Notably, we observed the nucleus localization of ZFP91 in colon cancer cells, implying that ZFP91 may exert nuclear functions." (PMID 27144516, 2016). "Our results suggest that ZFP91 may serve as a driver gene in the development of cancer and has potential as a relevant clinical indicator of disease progression and as a prognostic marker for patient survival in human colon cancer." (PMID 27144516, 2016). "We found that ZFP91 levels were downregulated in HCC, whereas ZFP91 expression was upregulated in AML, prostate and colon cancers 30-32." (PMID 32754263, 2020). "ZFP91 was shown to be upregulated in human acute myelogenous leukemia (AML), prostate cancer and colon cancer 30-32." (PMID 32754263, 2020). "However, the clinical significance and biological role of ZFP91 in colon cancer remains unknown." (PMID 27144516, 2016). "In terms of the mechanism, ZFP91 functions as a driver gene to activate NF-κB/p65, which results in the upregulation of HIF-1α expression, ultimately leading to the excessive proliferation of colon cancer cells." (PMID 36358661, 2022). "We found that ZFP91 upregulated HIF-1α at the levels of promoter and protein in colon cancer cells." (PMID 27144516, 2016). "Naturally, the overexpression of HIF-1α upregulated VEGF and EPO protein and mRNA levels in the cells (lane 5), silencing of HIF-1α abolished the upregulation of VEGF and EPO protein and mRNA levels mediated by ZFP91 (lane 4), supporting that ZFP91 is able to upregulate HIF-1α in colon cancer cells." (PMID 27144516, 2016). "Thus, we concluded that ZFP91 activates transcriptional coregulatory protein HIF-1α through transcription factor NF-κB/p65 in the promotion of proliferation and tumorigenesis in colon cancer cell." (PMID 27144516, 2016). "Interestingly, ZFP91 mRNA and protein levels are downregulated in all six primary HCC tissue samples compared with matched adjacent nontumoral hepatic tissue samples, which is inconsistent with previous studies in which ZFP91 expression is upregulated in AML, prostate and colon cancer tissues 30-32." (PMID 32754263, 2020). "Furthermore, IHC assay showed that areas of strong ZFP91 signals displayed intense HIF-1α, VEGF and CD31, whereas areas with knockdown of HIF-1α exhibited lower HIF-1α, VEGF and CD31 staining signals in ZFP91-overexpressing colon cancer cells." (PMID 27144516, 2016).
gastric cancer (11 papers, 2014 to 2024). A primary or metastatic malignant neoplasm involving the stomach. "The regulatory role of MALAT1 in oxaliplatin (OXA) resistance in gastric cancer cells is mediated by its interaction with ZFP91 through miR-22-3p sponging." (PMID 38370477, 2024). "Moreover, the intricate relation of miR-188-5p and ZFP91 was also reported in acute myeloid leukemia 43 and gastric cancer." (PMID 35399733, 2022). "Furthermore, ZFP91 was found to be overexpressed in malignant breast cancer and stomach cancer cell lines having high NF-κB activity in comparison with cell lines having lower NF-κB activity." (PMID 24272675, 2014). "Zinc mainly contributes to gastric cancer cell resistance through zinc finger proteins such as ZFP64, GLI1, ZFP91, ZNF139, which regulate gastric cancer cell resistance through pathways such as GAL-1, MALAT1, AKT-mTOR, or by modulating miRNA." (PMID 38370477, 2024). "Our previous study showed that ZFP91 is a downstream effector of ECD and ECD blocks the polyubiquitination and degradation of hnRNP F of ZFP91 in gastric cancer." (PMID 32754263, 2020). "The protective factor AP001350.1 gene, a novel lncRNA antisense to ZFP91, was not yet clear about its role in GC, but high expression of ZFP91 promotes proliferation and invasion of gastric cancer." (PMID 37408779, 2023).
prostate carcinoma (10 papers, 2014 to 2025). A carcinoma that arises from epithelial cells of the prostate gland. "Lower ZFP91 expression in samples with Gleason score 6 is an interesting result as it represents a low-risk prostate cancer and efforts are still being made to distinguish low- and high-risk disease." (PMID 27975057, 2016). "ZFP91 has been described as a promoter of carcinogenesis in prostate cancer and myelogenous leukemia." (PMID 32630670, 2020). "QPCR analysis revealed marked upregulation of ZFP91 mRNA in the majority of prostate cancer specimens." (PMID 27975057, 2016). "The present study is the first to our knowledge that directly tests the inhibition of ZFP91 expression in prostate cancer cell lines using RNA interference." (PMID 27975057, 2016). "A siRNA mediated knockdown of the ZFP91 gene revealed a potential accumulation of the ZFP91 protein in prostate cancer cells." (PMID 27975057, 2016). "Samples with Gleason score 6 prostate cancer had ZFP91 expression similar to control group, that is, significantly lower." (PMID 27975057, 2016). "In order to explore the significance of ZFP91 in prostate cancer biology further studies are definitely needed." (PMID 27975057, 2016). "Studies on ZFP91 gene's potential role in prostate cancer pathogenesis seem important not only due to its oncogenic properties." (PMID 27975057, 2016). "In the current study, the ZFP91 gene expression was examined in prostate cancer specimens and found to be markedly upregulated." (PMID 27975057, 2016). "The results of the present study show significantly elevated expression of ZFP91 mRNA in prostate cancer samples compared with normal prostate, in some cases over 10-fold." (PMID 27975057, 2016). "On the other hand, prostate cancer cell lines and normal prostate epithelial cells had similar ZFP91 mRNA levels; however protein abundance was clearly the highest in cancer cell lines." (PMID 24272675, 2014). "On the other hand, ZFP91 relative abundance in prostate cancer cells, together with the promising field of ZFP91 potential interactions, makes it a novel interesting target of studies." (PMID 24272675, 2014). "In conclusion, the upregulated ZFP91 mRNA in BPH, not accompanied by parallel changes in ZFP91 protein levels, together with ZFP91 protein abundance in prostate cancer cell lines suggest ZFP91 involvement in these prostate diseases." (PMID 24272675, 2014). "More importantly, ZFP91 has also been shown to be an oncogene for prostate cancer." (PMID 34925523, 2021). "The results presented in this study indicate that ZFP91 is overexpressed in prostate cancer." (PMID 27975057, 2016). "Taking this into consideration, together with a fact that ZFP91 protein knockdown was established in other cell lines, it may be hypothesized that in case of prostate cancer cells ZFP91 protein is accumulated or stabilized." (PMID 27975057, 2016). "Protein levels of ZFP91 were examined in prostate cancer cells treated with ZFP91 siRNA." (PMID 27975057, 2016). "The present study aimed to characterize ZFP91 expression in prostate cancer specimens." (PMID 27975057, 2016). "We conclude that ZFP91 is overexpressed in prostate cancer and that potential accumulation of the ZFP91 protein in studied cells may be of importance in prostate cancer biology." (PMID 27975057, 2016). "This indicates that ZFP91 protein may be stabilized and accumulated in prostate cancer cells and this effect may be connected with oncogenic properties of ZFP91." (PMID 27975057, 2016). "Marked overexpression of ZFP91 in many samples of prostate cancer remains unclear and requires further investigation." (PMID 27975057, 2016). "Recently, ZFP91 zinc finger protein has been found to be upregulated in prostate cancer cell lines." (PMID 27975057, 2016). "Taking this into consideration, ZFP91 may potentially influence androgen receptor signaling in prostate cancer cells and therefore affect the biology of prostate cancer." (PMID 27975057, 2016).
prostate carcinoma (continued). "Furthermore, since our earlier reports showed discrepancies between ZFP91 mRNA and protein levels, we studied this interrelationship in LNCaP and PC-3 prostate cancer cell lines using siRNA mediated knockdown." (PMID 27975057, 2016). "What is important, ZFP91 relative abundance in prostate cancer cells may play a role in this cancer biology." (PMID 27975057, 2016). "In the light of our studies it seems legitimate to suggest that ZFP91 functioning may influence androgen-dependent genes expression and prostate cancer biology." (PMID 24272675, 2014). "Until now, knowledge regarding ZFP91 expression in prostate was limited to Northern blot confirmation of mRNA transcript presence in prostate, and finding of increased mRNA expression levels in prostate cancer specimens compared to unchanged prostate (by in situ hybridization)." (PMID 24272675, 2014). "In 2014 our team described changes in expression of little-studied ZFP91 zinc finger protein gene (ZFP91) in benign prostate hyperplasia (BPH) and in prostate cancer cell lines." (PMID 27975057, 2016). "As found in our previous work, similar ZFP91 mRNA overexpression was not noted in prostate cancer cell lines, despite upregulated ZFP91 protein levels in these cells." (PMID 27975057, 2016). "Taking into consideration known ZFP91 functions, this could play a role in NF-κB and HIF-1α signaling in prostate cancer." (PMID 27975057, 2016).